KANSL1 (KAT8 regulatory NSL complex subunit 1)
Description:
Non-catalytic component of the NSL histone acetyltransferase complex, a multiprotein complex that mediates histone H4 acetylation at 'Lys-5'- and 'Lys-8' (H4K5ac and H4K8ac) at transcription start sites and promotes transcription initiation. The NSL complex also acts as a regulator of gene expression in mitochondria. In addition to its role in transcription, KANSL1 also plays an essential role in spindle assembly during mitosis. Associates with microtubule ends and contributes to microtubule stability.
Synonyms: hMSL1v1; CENP-36; KIAA1267; MSL1V1; NSL1; DKFZP727C091; C17DELq21.31; DEL17Q21.31; KDVS
Tractability: PROTAC: UniProt records ubiquitination sites on it; ubiquitination databases record sites on it; its protein half-life has been measured.
Gene: Protein-coding gene on chromosome 17 (46,029,916 to 46,225,389, reverse strand). Ensembl gene ENSG00000120071.
Subcellular location: Nucleus; Chromosome, centromere, kinetochore; Mitochondrion; Cytoplasm, cytoskeleton, spindle pole
Subcellular location (Human Protein Atlas): Nucleoplasm
Pathways (Reactome):
Chromatin organization: HATs acetylate histones
Gene expression (Transcription): Formation of WDR5-containing histone-modifying complexes
Gene Ontology:
Molecular function: protein binding; histone acetyltransferase binding
Biological process: regulation of mitochondrial transcription; positive regulation of DNA-templated transcription
Cellular component: histone acetyltransferase complex; mitochondrion; MLL1 complex; NSL complex; nucleoplasm; nucleus; H4 histone acetyltransferase complex; spindle pole
Genetic constraint (gnomAD): Loss-of-function variants: 21 observed, 93.15 expected, observed/expected ratio (o/e) 0.23, 90% interval 0.16 to 0.32. The upper end of that interval is the gene's LOEUF score, 0.32, which puts it in group 1 of 6, group 1 being the genes least tolerant of losing a copy. Missense variants: 1,257 observed, 1,347.1 expected, observed/expected ratio (o/e) 0.93, 90% interval 0.89 to 0.98. Synonymous variants: 571 observed, 511.05 expected, observed/expected ratio (o/e) 1.12, 90% interval 1.04 to 1.2.
Gene-disease validity (ClinGen):
ClinGen rates the evidence that KANSL1 causes each of these diseases.
Koolen-de Vries syndrome (autosomal dominant): Definitive. A chromosomal anomaly characterized by developmental delay, childhood hypotonia, facial dysmorphism, and a friendly/amiable behavior.
Homologues: Orthologues: chimpanzee KANSL1 (99% identical), macaque KANSL1 (99% identical), rabbit KANSL1 (95% identical), pig KANSL1 (95% identical), rat Kansl1 (92% identical), guinea pig KANSL1 (92% identical), mouse Kansl1 (92% identical), zebrafish kansl1b (42% identical), zebrafish kansl1a (39% identical), tropical clawed frog kansl1 (39% identical), Drosophila melanogaster nsl1 (22% identical). Paralogues in human: KANSL1L (23% identical).
Diseases named in the same sentence as KANSL1 in open-access papers:
KANSL1 is named in the same sentence as 94 diseases in open-access papers, as found by Europe PMC text mining. Sharing a sentence is not in itself a finding about the gene and the disease. The quoted sentences say what the papers report.
Koolen-de Vries syndrome (26 papers, 2015 to 2026). "Koolen-de Vries syndrome (KdVS), caused by haplo-insufficiency of the KANSL1 gene, is a rare neurodevelopmental disorder characterized by hypotonia, intellectual disability, facial dysmorphism, and multi-system end-organ involvement." (PMID 41631283, 2026). "Loss of function variants in exon 2 of KANSL1 (e.g. G306*) are known to cause Koolen De Vries syndrome (KdVS), but variants in exon 8 identified on the H2 haplotype have not been associated with neurodevelopmental disorders." (PMID 38812061, 2024). "Koolen-de Vries syndrome, partially characterised by developmental delays and behavioural features, is caused by microdeletions or loss-of-function mutations in KANSL1." (PMID 37553252, 2023). "KANSL1 haploinsufficiency is associated with the neurodevelopmental disorder Koolen-de Vries syndrome (KdVS), also known as 17q21.31 microdeletion syndrome." (PMID 36743289, 2022). "Improving our understanding of transcription of NSL target genes is imperative given that haploinsufficiency of KANSL1 is causative of the debilitating Koolen-de Vries syndrome." (PMID 32382029, 2020). "Massive parallel sequencing of 70 genes in a girl with a suspicion of chromatinopathy detected the (NM_015443.4:)c.985_986delTT variant in exon 2 of KANSL1, which led to a diagnostic consideration of Koolen De Vries syndrome." (PMID 33050294, 2020). "KANSL1 haploinsufficiency causes Koolen-de Vries syndrome (KdVS), characterized by dysmorphic features and intellectual disability; amiable personality, congenital malformations and seizures also commonly occur." (PMID 29352316, 2018). "Heterozygous loss-of-function mutations and deletions of KANSL1 cause Koolen-de Vries syndrome (KdVS; OMIM 610443) which is characterized by intellectual disability and a characteristic facies." (PMID 29352316, 2018). "Next, integration of SNV and CNV data confirmed KANSL1 as sufficient for causation of Koolen-de Vries syndrome." (PMID 29179772, 2017). "We further determine that gorillas exhibit an independent duplication of the KANSL1 gene which may predispose them to Koolen-de Vries syndrome causing microdeletions." (PMID 41040191, 2025). "Koolen-de Vries syndrome was detected in one fetus (KANSL1 variant)." (PMID 37535131, 2024). "Pathogenic variants in KANSL1 and 17q21.31 microdeletions are causative of Koolen-de Vries syndrome (KdVS), a neurodevelopmental syndrome with characteristic facial dysmorphia." (PMID 38282074, 2024). "Mutation in KAT8 regulatory NSL complex unit 1 (KANSL1) or 17q21.31 microdeletion encompassing KANSL1 cause Koolen-de Vries syndrome (KdVS, OMIM #610443)." (PMID 35625553, 2022). "Koolen-de Vries syndrome (KdVS) is a rare disorder caused by haploinsufficiency of KAT8 regulatory NSL complex subunit 1 (KANSL1), which is characterized by intellectual disability, heart failure, hypotonia, and congenital malformations." (PMID 35177641, 2022). "Some KANSL1 mutations have resulted in Koolen-de Vries syndrome (KdVS) (OMIM #610443), characterized by developmental delay, intellectual disability, hypotonia, epilepsy, characteristic facial features, and congenital malformations in multiple organs." (PMID 28881586, 2017). "These potentially targetable disorders include NDDs like Coffin-Siris syndrome (ARID1B; OMIM: 105830), Kleefstra syndrome (EHMT1; OMIM:610253), and Koolen-De Vries syndrome (KANSL1; OMIM: 610443)." (PMID 40400017, 2025). "Koolen-de Vries syndrome (KdVS) is a rare multisystem genetic disorder due to deletions in the KANSL1 gene." (PMID 40486408, 2025). "KANSL1 is a critical gene in neurological development and function, as highlighted by its involvement in Koolen de Vries syndrome (KdVS)." (PMID 39154163, 2024). "These include Coffin-Siris syndrome (ARID1B), Koolen-de Vries syndrome (KANSL1), Kabuki syndrome (WDR5), and Kleefstra syndrome (WDR5)." (PMID 36743289, 2022).
Koolen-de Vries syndrome (continued). "It is essential in Drosophila, and haploinsufficiency of the human KANSL1 subunit results in the Koolen-de Vries syndrome." (PMID 32382029, 2020). "The MOF acetyltransferase-containing Non-Specific Lethal (NSL) complex is a broad transcription regulator and haploinsufficiency of its KANSL1 subunit results in the Koolen-de Vries syndrome in humans." (PMID 32382029, 2020). "Following the detection of the loss-of-function variant c.985_986delTT (NP_056258.1:p.Leu329Glufs*22) in exon 2 of KANSL1, a preliminary diagnosis of Koolen De Vries syndrome was made." (PMID 33050294, 2020). "The same year, at five years old, he was diagnosed with Koolen-de Vries syndrome due to heterozygous de novo mutation, c.611dupG, causing an amino acid change p.Met205TyrfsX9 variant in the lysine acetyltransferase 8 regulatory non-specific lethal complex subunit 1 (KANSL1) gene." (PMID 40115715, 2025). "Microarray-based CNV detection in children with ID compared to unaffected controls led to further refinement of the 17q21.31 microdeletion (Koolen-de Vries syndrome) region to only two genes, namely MAPT and KANSL1." (PMID 29179772, 2017).
Intellectual disability (11 papers, 2015 to 2025). "KdVS, resulting from mutations in the KANSL1 gene, is characterized by developmental delay, intellectual disability, and distinctive facial features." (PMID 38790268, 2024). "Individuals with variants in KANSL1, SETBP1, and CDK13 have intellectual disability that falls within the mild‐to‐moderate range." (PMID 39846212, 2025). "KdVS, caused by deletions or mutations in the KANSL1 gene, is characterized by developmental delays, intellectual disability, and distinct facial features, underscoring the importance of KANSL1 in brain development and cognitive function." (PMID 39154163, 2024). "Many of these genes have been previously implicatedwith human phenotypes, including developmental delay (e.g. ASPM, AFF3 and MAPT) and intellectual disability (e.g. NEMF, PI4KA and KANSL1)." (PMID 31757203, 2019).
Parkinson disease (9 papers, 2014 to 2025). A progressive degenerative disorder of the central nervous system characterized by loss of dopamine producing neurons in the substantia nigra and the presence of Lewy bodies in the substantia nigra and locus coeruleus. "While we identified ASE sites within MAPT, we also identified four sites of ASE in KANSL1, suggesting that the high Parkinson’s disease risk H1 allele is associated with lower KANSL1 expression, consistent with our functional assessment." (PMID 36074904, 2022). "While our data do not exclude a possible association between the MAPT gene and Parkinson’s disease, they provide strong evidence that KANSL1 plays a crucial role in the disease." (PMID 36074904, 2022). "Furthermore, we explored the possibility that Parkinson’s disease risk might be mediated at this locus through an effect on KANSL1 expression." (PMID 36074904, 2022). "Dementia-related genes ARHGAP27, CYP1B1, KANSL1, KRTCAP2, LSM7, and GBA are also linked to altered behavior, neurodegeneration, inflammation, and Parkinson’s." (PMID 37588516, 2023). "Within the adult cortical analysis, KANSL1 and LINC02210 (chr17q21.31 cluster identified in the fetal analysis) were associated with eQTLs that were associated with brain-related traits (e.g., mood traits and Parkinson’s disease)." (PMID 40000109, 2025). "Within the fetal PPIN, a common group of genes (i.e., KANSL1, LINC02210, RP11-259G18.3, MAPT-AS1, RP11-259G18.1, and MAPT) were associated with most of the mood/brain-related phenotypes (e.g., neuroticism, Parkinson’s disease, depression, mood swings, and white matter microstructure)." (PMID 37553252, 2023). "Meanwhile, six genes near MAPT in chromosome 17 including MAPT-AS1, SPPL2C, CRHR1, KANSL1, NSF, and WNT3 have been identified as risk genes by earlier GWAS for Parkinson’s disease, another common neurodegenerative disorder which might present clinical symptoms of FTD." (PMID 35509074, 2022).
developmental delay (7 papers, 2019 to 2025). "Pathogenic variants or deletion of KANSL1 underlie Koolen–De Vries syndrome (MIM 610443) which presents with developmental delay, intellectual impairment, and distinctive facial features." (PMID 41438488, 2025). "Koolen–de Vries syndrome (KdVS), due to 17q21.31 microdeletions or pathogenic KANSL1 gene mutations, is clinically characterized by congenital malformations, neonatal hypotonia, developmental delay, and facial dysmorphism." (PMID 38397281, 2024). "KdVS is neurodevelopmental disorder caused by mutations with loss-of-function in KANSL1 gene and patients with KdVS manifest epilepsy, congenital malformations and developmental delay." (PMID 34920755, 2021).
ovarian carcinoma (7 papers, 2013 to 2025). A malignant neoplasm originating from the surface ovarian epithelium. "KANSL1 has also been reported as frequently amplified or rearranged in ovarian cancer and mutated in relapsed acute myeloid leukaemia (AML)." (PMID 37161535, 2023). "A study on human ovarian cancer found that KANSL1 is amplified and/or rearranged in ovarian cancer, associated with the lymphocyte profile, a biomarker for response to histone deacetylase inhibition, and could potentially drive the expression of genes related to immune response." (PMID 38601075, 2024). "A recent study suggests KANSL1 may be a biomarker for improved survival and HDAC inhibition in ovarian cancer." (PMID 37087441, 2023).
COVID-19 (6 papers, 2021 to 2024). A disease caused by infection with severe acute respiratory syndrome coronavirus 2. "Among these overlapping genes, nonsynonymous SNPs in the exons across SPPL2C, CRHR1, MAPT, STH, and KANSL1 genes were identified, among which, 13 were from COVID-19 critical illness and 15 were from COVID-19 hospitalization." (PMID 39764106, 2024). "For the severity COVID-19 predictive mixed model the variables included were sex, body mass index (BMI), presence of comorbidities, and the genetic variants rs2232354, rs11385942 and rs1819040, belonging to the genes IL1RN, LZTFL1 and KANSL1, respectively." (PMID 38605121, 2024).
leiomyoma (6 papers, 2012 to 2025). A well-circumscribed benign smooth muscle neoplasm characterized by the presence of spindle cells with cigar-shaped nuclei, interlacing fascicles, and a whorled pattern. "Sarcomas with KAT6B/A::KANSL1 fusion were first described in one retroperitoneal and one uterine tumor originally diagnosed as leiomyoma, followed shortly after by a tumor initially diagnosed as uterine leiomyosarcoma." (PMID 39627614, 2025). "Six of the tumors were originally diagnosed as LG-ESS, one as leiomyoma, one as leiomyosarcoma, and the last case (in which molecular testing was a part of the diagnostic work-up) as a sarcoma with the KAT6B::KANSL1 fusion." (PMID 39627614, 2025). "Although KAT6B rearrangements have been reported in leiomyomas, rare examples of uterine leiomyosarcoma and acute myeloid leukemia, fusions involving KANSL1 are rare." (PMID 31027501, 2019). "Additionally, three cases of smooth muscle tumors with KAT6B::KANSL1 fusion were described in the literature, two of which were diagnosed as leiomyomas and one as a leiomyosarcoma." (PMID 39627614, 2025). "Six of those had been originally diagnosed as LG-ESS, one as leiomyoma, one as leiomyosarcoma, and the remaining case as sarcoma with the KAT6B/A::KANSL1 fusion." (PMID 39627614, 2025).
Alzheimer disease (5 papers, 2017 to 2025). A progressive, neurodegenerative disease characterized by loss of function and death of nerve cells in several areas of the brain leading to loss of cognitive function such as memory and language. "Both KANSL1 and MAPT have been linked to neurodegenerative diseases such as Alzheimer’s disease (AD), Progressive supranuclear palsy (PSP) and PD." (PMID 41394315, 2025). "A lot of SNPs associated with risk for Alzheimer’s disease (AD) were identified near MAPT and KANSL1 in humans, and they appeared to be correlated with an overexpression of both genes in different brain regions." (PMID 40729198, 2023). "Several SNPs associated with risk for Alzheimer’s disease (AD) were identified near MAPT and KANSL1 in humans and they appeared to be correlated with an overexpression of both genes in different brain regions." (PMID 28704368, 2017).
sarcoma (4 papers, 2024 to 2025). A usually aggressive malignant neoplasm of the soft tissue or bone. "The mutation landscape varies within the group of sarcomas with the KAT6B/A::KANSL1 fusion, as does the mRNA expression within this group (PCA analysis) and both might be linked to differences in clinical behavior." (PMID 39627614, 2025). "The differential diagnosis of sarcomas with KAT6B/A::KANSL1 fusion showing low-grade features mainly includes tumors with endometrial stromal or smooth muscle differentiation." (PMID 39627614, 2025). "The expression of WT1 seems to be at most focal and weak in most sarcomas with KAT6B/A::KANSL1 fusion, and 50% of the analyzed cases were entirely negative, which would be unusual for LG-ESS." (PMID 39627614, 2025). "Since they were originally described, another study reported a series of 12 patients with tumors classified as sarcomas with KAT6B/A::KANSL1 fusion." (PMID 39627614, 2025). "In another recent study, the authors focused on methylation profiling and copy number alterations in 18 sarcomas with KAT6B/A::KANSL1 fusion." (PMID 39627614, 2025). "According to current knowledge, sarcomas with KAT6B/A::KANSL1 fusion cannot be diagnosed based only on morphological and immunohistochemical features." (PMID 39627614, 2025). "Histologically, KAT6B/A::KANSL1 fusion sarcomas exhibit overlapping morphologic features with both endometrial stromal and smooth muscle tumors, sometimes with sex cord-like pattern, which can make diagnosis challenging." (PMID 41463261, 2025). "The correct diagnosis of sarcoma with KAT6B/A::KANSL1 fusion is of utmost importance, given that these tumors tend to behave aggressively even in cases which exhibit deceptively bland morphology." (PMID 39627614, 2025). "In comparison, none of the 7 out of 8 patients with tumors in the core KAT6B/A::KANSL1 sarcoma cluster, where follow-up was available, died from disease." (PMID 39392508, 2024). "According to the current knowledge, due to the overlapping features between endometrial stromal and smooth muscle differentiation, sarcomas with the KAT6B/A::KANSL1 fusion cannot be diagnosed based only on the morphological and immunohistochemical features, and molecular testing is needed." (PMID 39836188, 2025). "Moreover, recently described sarcomas with the KAT6B/A::KANSL1 fusion usually have overlapping features between LG-ESS/endometrial stromal nodule (ESN) and smooth muscle tumors." (PMID 39836188, 2025). "The morphology of sarcomas with KAT6B/A::KANSL1 fusion is variable, but almost all cases exhibited some features suggestive of endometrial stromal differentiation (fibroblastic or fibromyxoid) or hybrid features between endometrial stromal and smooth muscle differentiation." (PMID 39627614, 2025). "KAT6B/A::KANSL1 fusion sarcoma is a recently recognized and distinct subtype of uterine sarcoma defined by a characteristic gene fusion involving KAT6B or, less commonly, KAT6A and KANSL1." (PMID 41463261, 2025).
Uterine leiomyoma (4 papers, 2015 to 2024). The presence of a leiomyoma of the uterus. "This was followed by case reports describing a rapidly enlarging KAT6B::KANSL1 uterine leiomyoma in a postmenopausal woman and a uterine leiomyosarcoma harboring a KAT6B::KANSL1 gene fusion." (PMID 39392508, 2024).
epilepsy (3 papers, 2017 to 2021). A brain disorder characterized by episodes of abnormally increased neuronal discharge resulting in transient episodes of sensory or motor neurological dysfunction, or psychic dysfunction. "Although the epilepsy phenotype in KdVS caused by heterozygous mutation of KANSL1 bears some resemblance to SFEC, this study did not provide strong evidence that KANSL1 variants contribute to the genetics of SFEC." (PMID 29352316, 2018).
schizophrenia (3 papers, 2023 to 2025). A major psychotic disorder characterized by abnormalities in the perception or expression of reality. "Within the fetal analysis, genes located in chr17q21.31, such as MAPT-AS1, KANSL1, LINC02210, MAPK8P1P2, and RP11-259G18.1, were regulated by eQTLs that have known associations with cognition, schizophrenia, and alcohol consumption traits." (PMID 40000109, 2025).